CD47 (CD47 molecule)
Diseases named in the same sentence as CD47 in open-access papers (continued):
Sharing a sentence is not in itself a finding about the gene and the disease.
cancer (continued). "In recent years, CD47 has been shown to be highly expressed by various types of solid tumors and to be associated with poor patient prognosis in various types of cancer." (PMID 32082311, 2020). "The presence of CD47 in AML was also associated with a high self-renewal potential of cancer stem cells and with low patient survival." (PMID 31921125, 2019). "SEs have been associated with CD47 in breast and other cancers, and constituent enhancers were identified." (PMID 30213113, 2018). "CD47 is overexpressed in many malignant tumors, which is closely associated with the malignant biological behavior of tumors, such as immunological evasion." (PMID 25658794, 2015). "In line with their immunosuppressive phenotype, several molecules, known to be linked to cancer progression and immune evasion, were highly expressed (>80%: CD47, CD274, CD276, and Indoleamine 2,3 dioxygenase-1)." (PMID 26618628, 2015). "The extracellular region of CD47 has been identified as crucial for its interaction with αvβ3, prompting our focus on understanding the biophysical mechanisms underlying the mutual stability and coexistence of these proteins on cancer cell membranes." (PMID 41168993, 2026). "CD47 is another target associated with macrophages for immunotherapies in HRD cancers." (PMID 40830526, 2025). "Interestingly, CD47 is a surface protein linked to cancer whose expression stops the innate immune system from identifying cancer cells, which promotes the growth of tumors." (PMID 40305328, 2025). "Aims to confirm whether the decreasing CD47 caused by GA could enhance the phagocytic ability of macrophages to cancer cells, the A2780 cells and THP-1 were co-cultured to examine the effect of GA (20 μM) on cell phagocytic ability." (PMID 40270598, 2025). "Interestingly, the co-expression of B7-H3 and CD47 in cancer cells was associated with larger tumors and greater invasiveness compared to tumors without such co-expression." (PMID 40214484, 2025). "CALR overexpression seemed to be an early stress event associated with TKIs treatment in vitro, and anti-CD47 treatment could increase phagocytosis of TKIs-exposed ALK+ cancer cells." (PMID 39767726, 2024). "One of the most popular CRC’ oncogenes in cancer is the CD47 gene—encoding a transmembrane protein which partners with integrins and binds membrane regulatory proteins—caused by aberrant SE constituents and helps cancer cells escape phagocytosis in B-cell lymphoma." (PMID 38542080, 2024). "High levels of either CD36 or CD47 are associated with poor outcomes for cancer patients." (PMID 39627379, 2024). "Pathways induced by PD-1 blockade in cancer immunotherapy have been closely linked to the upregulation of CD47 expression, indicating that elevated CD47 levels post PD-1 inhibitor treatment lead to a reduction in CD8 + T cells, ultimately contributing to drug resistance." (PMID 38720108, 2024). "Additionally, a high level of CD47 expression was found to be linked to substandard patient prognosis in different types of cancer." (PMID 38983860, 2024). "CD47 is also displayed on cancer cells, and increased expression was associated with worse outcome." (PMID 37217603, 2023). "Consequently, further research efforts are warranted to fully understand the underlying mechanisms of resistance and to optimize CD47-targeted therapies through innovative combination approaches, ultimately improving cancer treatment outcomes." (PMID 38188674, 2023). "CD47–TSP-1 binding has also been implicated in mediating sensitivity to cancer therapies." (PMID 37958404, 2023). "In this regard, our observations coalesce with those in the cancer field, as CD47 expression may be an intrinsic property and hallmark of senescence, aging, and oncogenic transformation." (PMID 36459066, 2023). "Besides these direct physical associations, CD47 has been discovered to indirectly interact with several other cytoplasmic proteins to regulate various cancer-relevant processes." (PMID 37958404, 2023).
cancer (continued). "We therefore propose that KRAS mutation status could serve as a biomarker for anti-CD47 cancer immunotherapy." (PMID 36413402, 2023). "Elevated CD47 expression is associated with low survival in these cancer patients." (PMID 37740183, 2023). "CD47 cannot be observed in the normal endometrium, but its expression is increased along with the progression of endometrial hyperplasia to carcinoma, and elevated CD47 expression was also associated with poorer prognosis and higher clinicopathological grade of EC." (PMID 37368179, 2023). "Correspondingly, high expression of CD47 is associated with poor prognosis in a range of cancers." (PMID 35908284, 2022). "Enhanced CD47 expression on cancer cells is associated with poor overall survival." (PMID 35328721, 2022). "In addition, high CD47 expression is usually associated with poor prognosis in cancer patients, thus showing potential as a prognostic marker." (PMID 36010209, 2022). "A direct association of CD47 expression by cancer cells and the % FOXP3+ TILs was also noted." (PMID 35406573, 2022). "Thus, the surface CD47 expression by cancer cells plays to their advantage by avoiding phagocytes, cancer-associated antigen presentation, and, eventually, T-cell priming." (PMID 36568151, 2022). "Importantly, adding back IL-1β and GM-CSF to SIRPγ-deficient cancer cells rescued CD47 expression, leading to inhibition of phagocytosis by macrophages and restoration of tumorigenesis." (PMID 35229723, 2022). "CD47 is an integrin-associated protein and is overexpressed in many cancer cells." (PMID 35211415, 2022). "High expression of CD47 is associated with poor survival in many cancers." (PMID 34093795, 2021). "Indeed, the augmented anti-cancer efficacy of RT conferred by Sirpα-deficient macrophages was unmatched by therapeutic combinations with anti-PD-L1 checkpoint inhibitors, CD47-blockade, and/or antitumor antibodies." (PMID 34050181, 2021). "These evidence suggested that the association of CD47 expression with patient’s prognosis might be dependent on a specific type of cancer." (PMID 33765961, 2021). "Moreover, CD47 positive GBM cells possessed many characteristics that associate with cancer stem cells, which implies worse clinical outcomes." (PMID 33329583, 2020). "As CD47 is tightly associated with a number of aggressive cancers, CD47 may serve as a positive predictive marker of cancer progression and metastasis." (PMID 32576895, 2020). "Using flow cytometry we further investigated whether CD47 mAb treatment causes cancer cell death in vitro." (PMID 30674867, 2019). "Loss of CD47 surface markers on cancer cells induced macrophage phagocytosis." (PMID 30674867, 2019). "We identify two distinct super-enhancers (SEs) associated with CD47 in certain cancer cell types." (PMID 28378740, 2017). "Interestingly, coating oncolytic herpes simplex virus with CD47 or on the opposite, targeting CD47 using antibodies encoded within oncolytic viruses has both been successfully developed as approaches to improve the antitumor innate immune responses to cancer." (PMID 37835397, 2023). "CD47 is expressed on T lymphocytes; when a CD47 antibody binds to CD47 on T lymphocytes, it may cause T-cell apoptosis, which may prevent clinical development, as T cells are key immune cells in cancer immunotherapy." (PMID 36882399, 2023). "Thus, we believe that blockade of the SIRPα/CD47 axis using a pan-allele SIRPα mAb provides a novel approach to immunotherapy that may be applicable for a broad range of cancers." (PMID 31801627, 2019). "Therefore, immunoaffinity enrichment of CD47+ EVs from blood and other body fluids could increase the sensitivity for detecting cancer-associated noncoding RNAs in liquid biopsies." (PMID 29416092, 2018). "Similarly, a CD47 variant was also developed for cancer immunotherapy." (PMID 27863402, 2016).
cancer (continued). "This review compares the structure, ligand interactions, and signaling mechanisms of SIRPα, SIRPβ, and SIRPγ, summarizes their roles in cancer, autoimmunity and neurodegeneration, and surveys therapeutic strategies that target the CD47-SIRPα axis." (PMID 41822520, 2026). "This experimental framework provides crucial insights into the CD47/αvβ3 interaction, laying a foundation for targeted disruption strategies with potential implications in cancer therapeutics." (PMID 41168993, 2026). "CD47/signal‐regulatory protein α (SIRPα) signaling enables malignant cells to evade macrophage‐mediated phagocytosis, offering a promising strategy for cancer therapy via immune checkpoint blockade." (PMID 41168993, 2026). "First, while prior research focused on the influence of CD47 on αvβ3 activation, our findings indicate that αvβ3 and CD47 on the membrane surface of cancer cells predominantly coexist in an inactivated conformer." (PMID 41168993, 2026). "High-dimensional cytometry confirmed discrete, cancer-enriched myeloid clusters expressing CD47, SIRPα, PD-L1, CD73, and Galectin-9." (PMID 41683933, 2026). "Many cancers, including hematologic malignancies and solid tumors, overexpress CD47 to escape immune-mediated clearance." (PMID 41601654, 2026). "CD47–SIRPα blockade is a strategy that aims to activate TAMs and other phagocytic cells against cancer cells." (PMID 41590379, 2026). "It is therefore plausible that the fundamental conformation in which αvβ3 and CD47 stably coexist on the surface of cancer cells resides in one or more intermediate states, likely in the form of a bent/extended closed intermediate conformation." (PMID 41168993, 2026). "It has been shown that overexpression of CD47 allows cells (such as in various cancers) to evade immune surveillance." (PMID 41557734, 2026). "This study identifies a cancer‐specific interaction between CD47 and integrin αvβ3 that facilitates immune evasion." (PMID 41168993, 2026). "Cluster of Differentiation 47 (CD47) functions as a key "don't-eat-me" signal that enables cancer cells to evade macrophage-mediated immune clearance." (PMID 41977514, 2026). "In this study, we used a FACS-based, genome-wide CRISPR-Cas9 knockout screening approach to identify genetic regulators of CD47 surface expression in murine cancer cells." (PMID 41601654, 2026). "To this end, we established a FACS-based, genome-wide CRISPR knockout screening pipeline targeting CD47 in three murine cancer cell lines (MC38, B16, and EMT6)." (PMID 41601654, 2026). "Computational chemistry was used to optimize DSP216 affinity to HLA-G with the aim to achieve the desired binding mode and DSP216 binding to CD47+/HLA-G+ and CD47+/HLA-G- cancer cells, PBMCs, and RBCs was tested." (PMID 41662489, 2026). "Through siRNA and shRNA experiments, we demonstrate the mutual stabilization of αvβ3 and CD47 on cancer cell membranes." (PMID 41168993, 2026). "This upregulation was accompanied by increased expression of multiple inhibitory ICPs (e.g., PD-L1, B7-H3, and CD47) compared with their parental adherent cells (cancer), suggesting a potential role for these ICPs in mediating CSC characteristics." (PMID 42027871, 2026). "The cell surface protein CD47, a “don’t-eat-me” signal overexpressed on cancer cells and connected to worse prognosis, interacts with the signal regulatory protein alpha (SIRPα) on phagocytes to overpower pro-phagocytic “eat-me” signals and prevent engulfment." (PMID 41590379, 2026). "By blocking this interaction, the anti-CD47 antibody magrolimab has been shown to unmask “eat-me” signals and induce macrophage-induced phagocytosis in cancer cell lines and ovarian cancer xenografts." (PMID 41590379, 2026). "CD47 is a signaling molecule that is substantially expressed in malignant tumors, allowing tumors to evade macrophage attack by giving a ‘do not eat me’ signal, whereas CD47 inhibition does the opposite." (PMID 40927726, 2025).
cancer (continued). "Our study offers a rationale for targeting macrophage infiltration or blocking CD47 to sensitize HDACi therapies in cancer patients." (PMID 39994810, 2025). "This strategy blocks checkpoint signaling pathways, including CD47/SIRPα and PD-1/PD-L1, thereby activating cancer photoimmunotherapy and reinvigorating antitumor macrophages and T cells." (PMID 40087690, 2025). "Targeting CD47 as a cancer treatment strategy has been extensively investigated in clinical settings in the past few years." (PMID 41383500, 2025). "High CD47 expression on cancer cells provides a strong “don’t eat me” signal by interacting with SIRPα on the surface of myeloid cells." (PMID 40385641, 2025). "In various malignant tumors, inhibiting the interaction between CD47 and SIRPα has been demonstrated to boost the phagocytosis of cancer cells by macrophages, promoting their clearance." (PMID 40385528, 2025). "High expression levels of cluster of differentiation 47 (CD47) have been recognized as poor survival in several different cancers." (PMID 40765033, 2025). "The primary reason is that CD47 lacks cancer specificity and is widely distributed in healthy tissues, leading to a substantial “antigen sink”; thus, high doses of anti-CD47 drugs are required to attain anticancer efficacy." (PMID 40589735, 2025). "A newly developed nano-immunotherapy uses nanoparticles loaded with anti-cancer drugs and dual-targeting antibodies (e.g., against CD47 and PD-L1) to deliver drugs directly to cancer cells." (PMID 41471095, 2025). "CD47, also known as integrin-associated protein (IAP), is often utilized by cancer cells to evade immune system surveillance and attack." (PMID 40861801, 2025). "In contrast, for cancer cells, CD47 was found to distribute as micro-clusters, while CD47 clusters diffused during cell apoptosis induced by ultraviolet irradiation, resulting in the clearance by macrophages." (PMID 39367479, 2025). "Further study is needed to define how the CD47+ EVs produced by activated B and T lymphocyte lineages regulate intercellular communication relevant to innate and adaptive immune responses in cancer and infectious diseases." (PMID 40943300, 2025). "Cancer cells overexpress CD47 to evade immune surveillance; thus, CD47 can be a target for immunotherapy." (PMID 40578556, 2025). "Considering that CD47 is a marker that is highly expressed in cancer cells and interacts with SIRPα to prevent their own phagocytosis, this pathway can be inhibited through anti-CD47 or anti-SIRPα therapy leading to more phagocytosis of cancer cells." (PMID 41142789, 2025). "Cancer cells frequently upregulate surface CD47, which ligates the inhibitory receptor SIRPα on Mφs to suppress phagocytosis." (PMID 41164198, 2025). "Since elevated CD47 mRNA expression correlates with poor prognosis of human cancers, CD47–SIRPα signaling plays an important role in cancer immune evasion and is a target for cancer immunotherapy." (PMID 40763927, 2025). "Beyond cardiovascular pathology, CD47 contributes to cancer, autoimmune diseases, metabolic disorders, and infection." (PMID 41303525, 2025). "Since the phagocytosis of cancer cells by phagocytic cells involves the inhibitory SIRPα-CD47 interaction and the facilitatory LRP-cancer cell membrane CALR interaction, blockade of the LRP-CALR interaction impedes phagocytosis 46,47." (PMID 39744689, 2025). "The blockade of CD47-SIRPΑ can enhance Mac-1 expression, accelerating the adhesion between macrophages and cancer cells and boosting the subsequent phagocytic process." (PMID 40046045, 2025). "Recent studies have focused on modifying the SIRP/CD47 pathway to influence innate immune cells, particularly macrophages, for cancer treatment." (PMID 41402667, 2025). "As with RBC membranes, CD47 plays a critical role in reducing phagocytosis of cancer cell-coated NPs (CM-coated NPs)." (PMID 41302542, 2025).
cancer (continued). "Background/Objectives: CD47 is a cell surface glycoprotein moderately expressed in healthy cells and upregulated in cancer and viral infected cells." (PMID 40573933, 2025). "Early studies indicated that CD47 formed micro-clusters in cancer cells and changed to a diffuse pattern during apoptosis." (PMID 39367479, 2025). "While normal cells use CD47 expression to avoid unintended phagocytosis, cancer cells exploit this pathway by overexpressing CD47 to evade immune detection and promote malignant progression." (PMID 41163221, 2025). "An evaluation of macrophage phagocytosis over a short period and residual cancer cells after a prolonged period revealed that CGs such as ouabain and digoxin significantly enhanced the macrophage killing effect mediated by CD47 antibody." (PMID 40985476, 2025). "Targeting signal regulatory protein-α (SIRPα) or CD47 to restore the phagocytosis activity of TAM is another immunotherapeutic approach being used to treat different cancers." (PMID 41019045, 2025). "Bioinformatics approaches were adopted to analyze how macrophage infiltration determines the prognostic significance of CD47 expression in cancer patients." (PMID 39994810, 2025). "Specific phagocytosis regulatory factors, such as the “don’t eat me” signals, including CD47, allow cancer cells to inhibit macrophage-mediated phagocytosis, facilitating immune escape and enhancing metastatic potential." (PMID 40396172, 2025). "Emerging clinical trials are examining the effectiveness of anti-CD47 mAbs and SIRPα-Fc fusion proteins in various cancers." (PMID 41350707, 2025). "Another notable finding was the significant expression of SIRPA, an inhibitory receptor on macrophages, and its ligand CD47, which is often overexpressed in cancers." (PMID 40788962, 2025). "CD47 is a critical “don’t eat me signal” biomarker which allows cancer cells to evade the innate immune defense." (PMID 40574837, 2025). "Given its essential role as a negative ICP, numerous efforts have been made to evaluate the therapeutic potential of targeting the CD47-SIRPα axis in cancer." (PMID 41233805, 2025). "Ad[CE1A] significantly altered ICD markers (CALR, CD47 and ATP) in a beneficial dose and time dependent manner, aligning with Ad-driven effects observed in other cancers." (PMID 40247106, 2025). "ICPs such as cluster of differentiation 47 (CD47) and programmed death ligand 1 (PD‐L1), frequently overexpressed by cancer cells, play critical roles." (PMID 39888280, 2025). "In cancer therapeutics, anti-SIRPα antibodies exert their antitumor effects by disrupting the CD47-SIRPα interaction and relieving inhibitory signaling on neutrophils)." (PMID 40589735, 2025). "Among these, CD47, a highly N-glycosylated 47–52 kD integral membrane glycoprotein, is overexpressed in numerous cancer types and is expressed in almost all normal cells, including red blood cells (RBCs) and platelets." (PMID 40129966, 2025). "In tumors, CD47 overexpression contributes to immune evasion by shielding cancer cells from immune surveillance." (PMID 40739089, 2025). "The active CD47/SIRPα signaling pathway drives evasion of immune surveillance in a variety of malignancies and therefore poses a greater challenge for cancer treatment, including PDAC." (PMID 41350707, 2025). "To date, clinical trials have been initiated with more than 20 antibody drugs that block CD47 as immunotherapies for cancers." (PMID 40185975, 2025). "Especially in cancer with high CD47 expression, additional blockade of the CD47/SIRPα axis has been shown to enhance IgA mAb efficacy." (PMID 40358156, 2025). "KPC and ID8 cancer cells were less susceptible to NDV infection as evidenced by lower numbers of GFP-positive cells and correspondingly lower numbers of CD47+ cells." (PMID 41322194, 2025).